EGFR (epidermal growth factor receptor)
Diseases named in the same sentence as EGFR in open-access papers (continued):
Sharing a sentence is not in itself a finding about the gene and the disease.
colorectal cancer (continued). "We then decided to investigate the correlation between both FISH and CISH EGFR GCN and clinical outcome in terms of response rate and time to progression (TTP) in irinotecan-refractory K-RAS wild-type colorectal cancer patients treated with irinotecan-cetuximab." (PMID 19712476, 2009). "Since the initiation of our study, it has become clear that response to EGFR-targeted therapy is not correlated with EGFR overexpression in the context of colorectal carcinoma." (PMID 19401697, 2009). "Our data are too limited to draw any definitive conclusion; nevertheless in our experience gefitinib does not increase the activity of FOLFOX combination in advanced colorectal cancer even in patients overexpressing EGFR or with EGFR amplification." (PMID 18059397, 2008). "However, to our knowledge, this study was the first to show a relation between Id-1 and EGFR and VEGF in colorectal cancers." (PMID 19014499, 2008). "The observed inverse correlation of EGFR activity with EGFR expression suggests a negative feedback loop between EGFR activity and expression in colorectal cancer cell lines"." (PMID 18691415, 2008). "Gefitinib does not seem to increase the activity of FOLFOX in advanced colorectal cancer even in patients overexpressing EGFR or with EGFR amplification." (PMID 18059397, 2008). "Tumour and non-tumour tissue specimens from 46 cases of colorectal carcinoma were exposed to immunohistochemical staining for Id-1, EGFR and VEGF." (PMID 19014499, 2008). "The aim of this study was to reveal whether there was a relationship between Id-1 and EGFR and VEGF in colorectal carcinoma." (PMID 19014499, 2008). "On the contrary, among 51 (52%) EGFR-positive primary colorectal cancers, 13 (25%) cases were negative for phosphorylated Akt and 15 (29%) were negative for phosphorylated MAPK." (PMID 17579627, 2007). "Among 51 (52%) EGFR-positive primary colorectal cancers, 13 (25%) cases were negative for phosphorylated Akt and 15 (29%) were negative for phosphorylated MAPK." (PMID 17579627, 2007). "The aim of this study was to determine the predictive and prognostic value of epidermal growth factor receptor (EGFR) expression in rectal cancers treated with preoperative high-dose rate brachytherapy and in mismatch-repair (MMR)-proficient colorectal cancers (CRCs), respectively." (PMID 17311026, 2007). "Using this approach, we showed significant inhibition of EGFR and ERK in the post-treatment samples, consistent with EGFR signalling playing an important role in the downstream activation of the ERK pathway in colorectal cancer, and the successful disruption of this pathway by erlotinib." (PMID 16570047, 2006). "Several studies have evaluated the prognostic significance of EGFR on survival in colorectal cancer but, to our knowledge, not specifically focusing on rectal cancer recurrence." (PMID 15967033, 2005). "Indeed, growth factor signaling via EGFR and downstream MAPK/PI3K cascades is a critical driver of cell proliferation and drug sensitivity in colorectal cancer, and its attenuation is consistent with the reduced responsiveness of TRIM28-KO cells to cytotoxic agents." (PMID 41303350, 2025). "Furthermore, in colorectal cancer cells, the EGFR/Kras pathway specifically upregulates TNS4, though without affecting TNS3, and in HeLa cells, the EGFR-activated RAF/MEK/ERK pathway facilitates p300 binding to the TNS4 promoter, enhancing its expression." (PMID 40906372, 2025). "Notably, in colorectal cancer, SPINK1 has been shown to activate the EGFR/MAPK signaling pathway, thereby promoting cancer progression, which may be related to the tissue-specific origin characteristics of the tumor." (PMID 40904507, 2025). "Sotorasib plus panitumumab, according to an approach of dual KRAS G12C and EGFR blockade, overcame treatment resistance in patients with colorectal cancer with KRAS G12C mutation, typically a population not responding to EGFR inhibitors, such as cetuximab and panitumumab." (PMID 39941081, 2025).
colorectal cancer (continued). "In a study, the combination of an EGFR-targeting oncolytic adenovirus (Onc.Ad-EGFR BITE) with folate receptor-alpha (FR-α)-specific CAR-T cells demonstrated improved tumour cell killing through the secretion of bispecific T-cell engagers (BITE) in pancreatic and colorectal carcinoma." (PMID 40624498, 2025). "In certain melanomas and colorectal cancers, inhibition of mutant BRAF suppresses oncogenic ERK signals but simultaneously relieves ERK-dependent negative feedback of RTKs, resulting in strong epidermal growth factor receptor (EGFR) stimulation, cell survival, and drug resistance." (PMID 39488530, 2024). "Similarly, a study has suggested that HDACis could function independently to inhibit both epidermal growth factor receptor (EGFR) and HDAC, potentially offering advantages in the therapies of KRAS mutant colorectal cancer." (PMID 38822399, 2024). "Furthermore, we validated ZNRF3/RNF43-EGFR signaling in prostate cancer, one of the several other tumors in patients besides colorectal cancer that showed a negative correlation ZNRF3/RNF43 mRNA and EGFR protein levels." (PMID 38260423, 2024). "Similarly, EGFR, a TSA, plays a crucial role in the development and progression of solid tumors and has emerged as a significant therapeutic target in various cancers such as NSCLC, breast, gastroesophageal, colorectal cancers, and GBM." (PMID 39697210, 2024). "Interestingly, our results indicated that PMP models did not present this feedback loop activation through EGFR observed in colorectal cancer." (PMID 39018564, 2024). "Although exploratory, our findings suggest that certain patients with right-sided colorectal cancer may benefit from first-line anti-EGFR antibodies with chemotherapy if negative hyperselection is feasible." (PMID 38347302, 2024). "However, the incidence of thromboembolism among Japanese patients with colorectal cancer treated with VEGF inhibitors has not been compared with that in patients administered EGFR inhibitors." (PMID 37394446, 2023). "Reports from Taiwan of KRAS wild-type colorectal cancer refractory to two or three regimens and from Italy of RAS/BRAF wild-type colorectal cancer refractory to two or three regimens both suggested that the therapeutic effect of anti-EGFR antibodies is better in left-sided colorectal cancer." (PMID 37760533, 2023). "Since the development of epidermal growth factor receptor (EGFR) targeted therapy, antiangiogenic drugs, and the use of intense triplet chemotherapy regimens based on fluoropyrimidines, oxaliplatin, and irinotecan, the treatment of colorectal cancer (CRC) has improved significantly." (PMID 38067284, 2023). "Certain indications suggest that EGFR and its ligands (epidermal growth factor (EGF), amphiregulin, HB-EGF, TGF-alpha) can be applied as serological biomarkers in relation to the prognosis and prediction of response to EGFR-targeted treatments in lung, ovarian, and colorectal cancer." (PMID 37626832, 2023). "For instance, since the concept that KRAS mutant colorectal cancer patients do not benefit from the addition of EGFR antibodies to the chemotherapy backbone was introduced, determination of RAS status has become part of the routine diagnostic workup in patients with advanced colorectal cancer." (PMID 34436668, 2022). "Additionally, it has been established that the levels of EGFR expression were not correlated with the clinical response to cetuximab or panitumumab in colorectal cancer patients." (PMID 33795829, 2021). "Moreover, therapeutic experiences clearly indicated that hEx3, unlike conventional anti-EGFR antibodies, was effective against colorectal cancer (CRC) cells with mutant KRAS, BRAF, or PIK3CA." (PMID 32666260, 2021).
colorectal cancer (continued). "Hence, GFHPD or anti-EGFR antibody therapy associated reduction in colonic OXPHOS activity but improved goblet cell differentiation points to metabolic reprogramming of colorectal carcinomas towards a low-energetic balanced metabolism, thereby preventing cell proliferation and CRC tumor progression." (PMID 34830971, 2021). "Here, we identify that Oligo-Fucoidan combined with cisplatin treatment induces ROS signaling in colorectal cancer cells which can be suppressed by antioxidants (NAC, MitoQ and DPI), demonstrating that Oligo-Fucoidan and cisplatin together induce the oxidative signaling axis of YY1/EGFR/MnSOD." (PMID 32059469, 2020). "There is about more than 80% of advanced colorectal cancers that do not respond to anti-EGFR mAbs." (PMID 31508364, 2019). "Overall, a meta-analysis concluded that tissue EGFR amplification status could not be demonstrated to be a consistent biomarker to predict the outcome from anti-EGFR therapies in colorectal cancer." (PMID 31058253, 2019). "HDAC-4/EGFR/ERK1/2 signaling has been shown to regulate colonocyte differentiation, supporting the hypothesis that HDAC might cooperate with EGFR signaling to promote colorectal cancer progression." (PMID 31370270, 2019). "Altogether, data from colorectal cancer and NSCLC suggest that p65BTK is an emerging actionable target in tumour cells resistant to chemotherapy and scarcely responsive to target therapy because of lack of EGFR mutation or presence of activated KRAS." (PMID 31200752, 2019). "In summary, widening the KRAS mutational and subtyping analysis of colorectal cancer patients beyond the KRAS ‘hotspot’ codons 12 and 13 is useful in identifying patients who should not be treated with anti-EGFR antibodies, either alone or in combination with other anticancer agents." (PMID 31881025, 2019). "Colorectal cancer cell lines cultured in similar laminin-rich ECM 3D conditions also exhibited changes in cellular morphology, phenotype and gene expression and were resistant to treatment with epidermal growth factor receptor (EGFR) inhibitors compared to cells cultured in 2D conditions." (PMID 30621226, 2019). "However, colorectal cancers harboring constitutive activating mutations in KRAS, NRAS and BRAF genes are not responsive to anti-EGFR therapy." (PMID 31711486, 2019). "The efficiency of SWCNTs conjugated with antibody C225, which could bind specifically with over-expressed EGFR in colorectal cancer cells and a chemotherapeutic drug called 7-Ethyl-10-hydroxy-camptothecin (SN38) was evaluated in three different colorectal cancer cell lines: HCT116, HT29 and SW620." (PMID 30347840, 2018). "Dysregulation of EGFR signaling through overexpression of the receptor or hyper-activation of its kinase activity is a common theme in several solid tumors including non-small cell lung cancer (NSCLC), head and neck cancer (HNSCC), colorectal cancer, breast cancer and glioblastoma multiforme." (PMID 30323890, 2018). "Of note, in contrast to what established for advanced colorectal cancer, in NSCLC, at present, the evidence that K-Ras mutations predict a lack of benefit from EGFR-targeting therapy is not strong enough to impose K-Ras status investigation before starting treatment." (PMID 28653990, 2017). "Taken together, our results indicate that the dysregulation of miR-193a-3p is involved in the tumorigenesis of colorectal cancer, particularly BRAF-mutant cancer, and is likely to affect drug sensitivities to anti-EGFR therapy in colorectal cancer regardless of BRAF mutational status." (PMID 29115941, 2017). "Although KRAS mutational status is an established negative predictor of response to anti-EGFR therapies in colorectal cancer, it is currently unknown if this status predicts response in patients with ABTC." (PMID 27853997, 2017).
colorectal cancer (continued). "Already this has been described in a small cohort of patients with colorectal cancer initially demonstrating KRAS wild-type tumors, which subsequently were noted to have molecular alterations (via serum analysis) including KRAS, NRAS, EGFR, and BRAF after treatment with anti-EGFR therapies." (PMID 28030802, 2017). "However, review of data showed that patients with colorectal cancer diagnosed as EGFR-negative by IHC testing also responded to treatment with cetuximab." (PMID 29246028, 2017). "In an attempt to understand the mechanism by which MAG-EPA mediates its antitumor effects in colorectal cancer cells, we determined whether this monoglyceride form of omega-3 modulates VEGFR and EGFR signaling pathways in tumor homogenates derived from control (untreated) and MAG-EPA-treated mice." (PMID 28869531, 2017). "Dianthin-panitumumab and dianthin-cetuximab immunotoxins engineered from the full length therapeutic IgG conjugated to recombinant dianthin similarly showed no killing of EGFR-overexpressing colorectal cancer cells when administered at concentrations below 10 nM." (PMID 27153091, 2016). "Therefore, whether dual blockade of EGFR and COX-2 pathways represents a rational approach to benefit colorectal cancer patients remains elusive." (PMID 27074568, 2016). "Therefore, the simultaneous targeting of EGFR/VEGF and COX-2 may aid in blocking mCRC progression and improve the efficacy of existing therapies in colorectal cancer." (PMID 26107817, 2015). "Our data support the notion that the combined inhibition of EGFR and COX-2 in colorectal cancer cells disturbs FOXM1/β-catenin axis impacting CSC subpopulation, and therefore might improve the efficacy of existing therapies in colorectal cancer." (PMID 26107817, 2015). "Approximately 30–50 % of colorectal tumors are associated with an abnormal KRAS gene, signifying that nearly half of patients with colorectal cancer (CRC) might respond to anti-epidermal growth factor receptor (EGFR) treatment, and the other half might not." (PMID 26425215, 2015). "Further, the presence of mutations in RAS family oncogenes is associated with a lack of response to targeted therapy: lung and colorectal carcinomas characterized by KRAS mutations and KRAS and NRAS mutations, respectively are unresponsive to treatment with anti-EGFR agents." (PMID 26435479, 2015). "In addition, some molecular biological markers (such as epidermal growth factor receptor, thymidylate synthase, p21, and CEA) may also influence the response of colorectal carcinoma to chemoradiotherapy." (PMID 26040453, 2015). "We did not observe any significant association between overall or progression-free survival, neither when considering all colorectal cancer patients nor for subgroup analyses (metastatic, anti-EGFR [epidermal growth factor receptor] treatment, or KRAS wild type)." (PMID 24890702, 2014). "In BRAF mutant colorectal cancer it has been learned that negative feedback pathways are stimulated by the constitutive activation of the MAPK pathway conferred by BRAF activating mutations and that these pathways act to diminish signaling through the EGFR." (PMID 25520658, 2014). "However, despite these advancements, it is clear that not all colorectal cancer patients with wild-type KRAS would gain benefit from anti-EGFR mAbs and objective responses have also been reported in patients with KRAS mutated tumours." (PMID 24609222, 2014). "For example, standard treatment guidelines recommend KRAS and NRAS testing for colorectal cancer patients and that patients with KRAS- and NRAS-mutated colorectal cancer not be treated with epidermal growth factor receptor inhibitors such as cetuximab and panitumumab." (PMID 25593991, 2014).
colorectal cancer (continued). "BRAF and EGFR (epidermal growth factor receptor) genes, which are important co-factors of KRAS gene in the EGFR signaling pathway in the carcinogenesis, invasion and metastasis of colorectal cancers, also have prognostic value for patients with metastasis of adenocarcinoma." (PMID 25297496, 2014). "Furthermore, several colorectal cancer cell lines (VAC0432, SNU-C5, HT29, KM20, WiDr) are considered valuable models of resistance to the B- Raf (V600E) inhibitor vemurafenib because of the high levels of EGFR expression." (PMID 23992330, 2014). "Is the lack of response in colorectal cancer due to the presence of additional anomalies that co-occur with BRAF mutations, or because BRAF inhibition causes feedback activation of EGFR, or because BRAF mutations are not driver abnormalities in colorectal cancer?" (PMID 25593991, 2014). "Two monoclonal antibodies, cetuximab and panitumumab, which target the epidermal growth factor receptor (EGFR), were approved in Europe and the United States for the treatment of metastatic colorectal carcinoma (CRC) in 2004 and 2007, respectively." (PMID 24765171, 2014). "One of the approaches to target a growth factor receptor is the inhibition of epidermal growth factor receptor (EGFR) by inhibiting EGFR tyrosine kinase using small-molecule inhibitors or antibody-induced receptor blockade in different human cancers, including colorectal cancer (CRC)." (PMID 23900414, 2013). "However, the factor(s) that we think will be important for drug activity based on preclinical models may end up not being the ideal or relevant target, as was the case with EGFR IHC expression for EGFR TKIs in NSCLC and for cetuximab in colorectal cancer." (PMID 23587187, 2013). "Also it has a role in predicting colorectal cancers with worse prognosis and in identifying colorectal cancers lacking BRAF mutation that are more likely to respond to epidermal growth factor receptor inhibitor therapy." (PMID 24759670, 2013). "However, EGFR expression determined by immunohistochemistry does not predict clinical outcomes of colorectal cancer (CRC) patients treated with cetuximab." (PMID 23824671, 2013). "Based on previous findings and published validated targets for miR-7 such as EGFR, PAK1, RAF1, IRS1/2 and CD98, it is fair to hypothesize that this miR may be involved in regulating intracellular signaling, growth and differentiation of colorectal cancers." (PMID 22529906, 2012). "Therefore, therapies that target the EGFR and/or HER2 may be effective in the chemoprevention and/or therapy of colorectal cancer." (PMID 22788833, 2012). "However, we did not observe the phosphorylation of EGFR at these residues when the cells were treated with low dose cisplatin and/or low dose UV-C in colorectal cancer cells (data not shown)." (PMID 22788833, 2012). "Although KRAS mutations are consistently associated with reduced overall and progression-free survival (PFS) and increased treatment failure rates among patients with advanced colorectal cancer treated with anti-EGFR antibodies, no genetic and molecular markers for BV have been found." (PMID 21407216, 2011). "And EGFR-negative colorectal cancer patients have been reported to respond to cetuximab treatment." (PMID 20565817, 2010). "Importantly, EGFR gene amplification status, but not EGFR tumor protein levels, is associated with response to EGFR-targeted therapies in NSCLC and colorectal cancers." (PMID 19636423, 2009). "Recently Jonker and co-workers assessed the value of the anti-EGFR therapy cetuximab on a large cohort of 572 patients with advanced EGFR-expressing colorectal cancers who failed to respond to previous chemotherapy, and found a significant improvement in overall survival in these patients." (PMID 18182986, 2008). "These negative results may be due to a lack of efficacy of small molecules inhibitors of EGFR in combination with chemotherapy as in colorectal cancer or to the lack of patient selection." (PMID 18059397, 2008).